FXYD6-FXYD2 (FXYD6-FXYD2 readthrough)
Gene: Protein-coding gene on chromosome 11 (117,820,163 to 117,876,667, reverse strand). Ensembl gene ENSG00000255245.
Genetic constraint (gnomAD): Loss-of-function variants: 12 observed, 24.36 expected, observed/expected ratio (o/e) 0.49, 90% interval 0.31 to 0.8. The synonymous counts are far from expectation, so gnomAD's model fits this gene poorly and the ratio says little. Missense variants: 189 observed, 173.44 expected, observed/expected ratio (o/e) 1.09, 90% interval 0.97 to 1.23. Synonymous variants: 83 observed, 57.63 expected, observed/expected ratio (o/e) 1.44, 90% interval 1.21 to 1.73.